Y_RNA (Y RNA )
Gene: Miscellaneous RNA gene on chromosome 7 (43,096,732 to 43,096,844, forward strand). Ensembl gene ENSG00000201933.
Homologues: Orthologues: chimpanzee Y_RNA (100% identical), macaque Y_RNA (98% identical). Paralogues in human: RNY1 (88% identical), Y_RNA (88% identical), Y_RNA (86% identical), Y_RNA (85% identical), Y_RNA (84% identical), RNY1P11 (83% identical), Y_RNA (83% identical), Y_RNA (82% identical), RNY1P13 (81% identical), Y_RNA (81% identical), RNY1P10 (80% identical), RNY1P7 (80% identical), and 96 more.